CD44 (CD44 molecule (IN blood group))
Diseases named in the same sentence as CD44 in open-access papers (continued):
Sharing a sentence is not in itself a finding about the gene and the disease.
breast carcinoma (continued). "For instance, in breast cancer, CSCs are commonly identified by the overexpression of surface markers such as CD24, CD29 (β1-intergrin), CD44 (and its variants), CD49f, CD61, CD70, CD90, and CD133." (PMID 38067114, 2023). "A recent study provided evidential support that correlated with our results on hsa-miR-29a/b-3p, which was significantly upregulated in the ER- fractions of MCF7 cells and also in CD44+/CD24− breast cancer stem cells (BCSCs)." (PMID 36834918, 2023). "The authors propose this delivery form as an effective nanomedicine to eliminate CD44-positive breast cancer stem cells." (PMID 36899854, 2023). "A CXCR4 antagonist (cyclam monomer) combined with a CD44 inhibitor (Star miR-34a) demonstrated antitumour and antimetastatic efficacy in breast cancer." (PMID 35468838, 2022). "CD44, also known as H-CAM is a stem-like a receptor that has been found to be over-expressed on solid cancers like prostate cancer, breast cancer, glioblastoma, colon cancer, and cervical cancer." (PMID 36712656, 2022). "Immunophenotyping revealed increased percentages of CD44+CD24− cells in the reversed breast cancer cell population." (PMID 36012742, 2022). "Because it inhibited the PI3K/Akt/mTOR signaling pathway and has been proven to reduce breast cancer stem cells (CD44+/CD24), it was identified as a candidate for the treatment of breast cancer." (PMID 36233051, 2022). "In contrast, RGD-free HAGM cryogels promote the spatial organization of CD44-positive breast cancer cells (4T1 and MDA-MB-231) and eventually facilitate tumor microtissue formation." (PMID 35198956, 2022). "Downregulation of the Wnt signaling pathway, cancer stem cell markers oct4, Notch1, EpCAM, and CD44 was a common mechanism encountered in many tested breast cancer cell lines with eugenol." (PMID 36362950, 2022). "The CD44/c‐Met signaling has also been identified as the key regulator for VM in Ewing sarcoma and breast cancers." (PMID 36226253, 2022). "Markers consistently altered at lower bufalin concentrations (20 nM) were C-Kit, the CSC marker ALDH1A1, and the EMT factor Slug, which has previously been shown to be a regulator of CD44+ CSCs in breast cancer." (PMID 36362141, 2022). "Though, cells expressing CD44 have been mentioned as breast cancer stem cells; however, a portion of neoplastic breast epithelium is expressing CD44 too." (PMID 36585652, 2022). "In this work, we have developed an electrochemically exfoliated GQDs-based highly sensitive electrochemical biosensor to detect the CD44 breast cancer biomarker for the first time." (PMID 36354475, 2022). "The obtained hybrid PNPs can be internalized into drug-resistant breast cancer cells by the hyaluronic acid/CD44-mediated endocytosis pathway and escape from the lysosome through the “proton sponge effect”." (PMID 35214154, 2022). "Overall, our results demonstrated that the Cy7-1/PG5-Cy5@LWHA nanoprobe entered CD44+ breast cancer cells through CD44-mediated endocytosis, and later localized to the endolysosomal compartments in the cytoplasm." (PMID 35303862, 2022). "MCF-7 cells are ER+, PR+, HER2+, and CD44+, being frequently employed as in vitro models for breast cancer as they mimic between 79% and 84% of the cases." (PMID 36145331, 2022). "These scaffolds were used to evaluate the role of CD44/HA-mediated signaling via cell-cell and cell-matrix interactions with CD44-positive breast cancer cells." (PMID 35198956, 2022). "All these findings suggest that CD44 plays a role in regulating FOXA2 localization in breast cancer cells." (PMID 36289750, 2022). "Collectively, this study highlights that CD44 promotes breast cancer metastasis by downregulating nuclear FOXA2." (PMID 36289750, 2022). "For example, this is the case with the lncROPM lncRNA, which is expressed in the CD44+ CD24−/low breast cancer stem cell population." (PMID 35954194, 2022). "The crucial role of CD44 in cancer metastasis has also been highlighted in other cancers, including breast cancer." (PMID 35565396, 2022).
breast carcinoma (continued). "Our tetracycline-off-inducible CD44 expression system previously established in mouse model, revealed that activation of CD44 with its major ligand hyaluronan (HA) promoted breast cancer (BC) metastasis to the liver." (PMID 36505828, 2022). "Patient CD44 studies have shown a direct correlation between serum CD44 levels and cancer occurrence in pancreatic cancer, lung cancer, breast cancer, prostate cancer, and head and neck carcinoma." (PMID 36421133, 2022). "In human breast cancer cells the aptamer-doxorubicin conjugate was found to inhibit the proliferation of overexpressed CD44 breast cancer cells thus improving targeted therapy." (PMID 35350751, 2022). "The cluster-determinant 44 (CD44) is a cell-surface glycoprotein, which is overexpressed on tumor cells’ surfaces, namely lung cancer, pancreatic cancer, and breast cancer tumors." (PMID 35875198, 2022). "It has been reported that human mammary carcinoma cells undergoing apoptosis reversal show enhanced tumorgenicity with a high percentage of CSC markers (CD44+/CD24−) in the reversed cells." (PMID 36474162, 2022). "CD44 is expressed on most circulating tumour cells, whereas matched breast cancer brain metastasis tissues less frequently express CD44." (PMID 36316684, 2022). "It has been reported that CD44 promotes stemness and metastasis in various cancers, including breast cancer." (PMID 36289750, 2022). "Next, we also studied the endocytosis of HDDA NBs using another CD44-overexpressed tumor cell line MDA-MB-231 (a triple-negative human breast cancer cell line)." (PMID 36319625, 2022). "Stemness markers have been studied to identify BCSC, such as CD44/CD24 expression lines, which have shown a significant association with distant metastatic breast cancer subtypes for TNBCs." (PMID 36120232, 2022). "For instance, stimulation of CD44 in breast cancer cells was demonstrated to activate Twist expression, thus regulating the EMT phenotype through lysyl oxidase activation." (PMID 35982951, 2022). "CD44 plays a pivotal role in promoting invasion and metastasis of a variety of tumors, including breast cancer." (PMID 35198956, 2022). "A more recent study showed that CD44 isoform switching gave rise to invasion and metastases in luminal breast carcinomas with CD44s high expressing cells responsible for migration." (PMID 35931675, 2022). "For example, after breast cancer metastasis, in sporadic pleural effusion, breast cancer cells are rich in CSC-like cell populations with high CD44 expression and low CD24 expression." (PMID 35151264, 2022). "In breast cancer tumor cells, CD44 modified by palmitoylation is considered to prevent cell migration, so a blocking of palmitoylation on the transmembrane proteins acts as a potential approach to inhibit tumors." (PMID 35733341, 2022). "Notable findings were that the cancer progression-associated genes CD44, as well as BRCA1, a classic breast cancer gene, were highly represented in the PPI network for PABC versus NPABC." (PMID 36035177, 2022). "KRT13 promoted the CD44+CD24− phenotype, a combination of breast cancer stem cell markers associated with invasion and poor prognosis." (PMID 35078507, 2022). "Inhibition of GRP78 by antibodies effectively reduced the cell surface expression of CD44 and the invasiveness of tamoxifen-resistant breast cancer cells." (PMID 35740372, 2022). "In breast cancer cells, whereas CD44 and ezrin localize in different membrane regions at resting state, CD44 association with rafts decreases and its interaction with ezrin increases after induction of migration." (PMID 36439249, 2022). "Breast cancer cells use integrin heterodimers and CD44 to migrate by engaging with collagen I and hyaluronan, respectively." (PMID 35200398, 2022). "In this study, the ESA+CD44+CD24− population of breast cancer, which has been widely used as a marker for breast cancer cells with stemness, was enriched in ReA cells as well as TSs." (PMID 36009455, 2022).
breast carcinoma (continued). "The proportion of early disseminated tumour cells with the CD44+CD24− phenotype in the bone marrow of patients with breast cancer was approximately 72%." (PMID 35563449, 2022). "Similar results were observed with CD24−/CD44+ BCSCs sorted from a human luminal breast cancer cell line, MCF-7." (PMID 35053617, 2022). "In highly invasive CD44 expressing breast carcinomas, tumor cells also activate MMP-2 and MMP-9 resulting in degradation of collagen type IV in vascular basement membranes." (PMID 36497364, 2022). "Further investigations into breast cancer have previously yielded fundamental marker discoveries including Mki67+ as a prognostic marker, Cd44+/Cd24+ as a breast cancer stem cell marker, and Trop2 as another therapeutic target." (PMID 36630696, 2022). "Our previous studies evaluated PTEN and pAkt protein and CD44/CD24 CSC marker expression in breast cancer tissues in the same cohort of African-American and Hispanic patients." (PMID 35053979, 2022). "The aim of this study was to investigate the impact of biochemical cues inherently present in a HA-based macroporous matrix on CD44-positive breast cancer modeling." (PMID 35198956, 2022). "It was also reported that CD24 contributes to anti-oxidant activity, and its elevated expression enhances oxidative stress in the CD44(+)/CD24(-) phenotype of breast cancer." (PMID 36497040, 2022). "While FAP-a-expressing active fibroblasts promote breast tumorigenesis and are implicated in an immunosuppressive environment, CD10+ GPR77+ as well as CD44+ active breast fibroblasts promote breast cancer stemness and chemoresistance." (PMID 36359766, 2022). "Our data indirectly confirm such an observation, because of the minimal presence of two stemness markers—CD44 and CD133—on apoCTCs which are associated with poor prognosis in breast cancer patients." (PMID 36012742, 2022). "In fact, breast cancer stem cells (BCSCs) were first identified in 2003 on the basis of the expression levels of cell surface antigens, CD44+ and CD24−, that account for high capacity of invasiveness, migration, and proliferation." (PMID 35800881, 2022). "The nanocomplex significantly enhanced the uptake of breast cancer MCF-7 cells through the active targeting of CD44 and HER2 antibodies." (PMID 36091467, 2022). "In this study, we analyzed breast cancer patient samples to evaluate CD44 expression using flow cytometry." (PMID 36289750, 2022). "In summary, this paper reports the development of an anticancer drug delivery system based on CD44-targeted nanoparticles for efficient epirubicin delivery to breast cancer cells." (PMID 35875198, 2022). "HA has also been used to modify Au-Ag alloy NPs to target CD44-expressing 4 T1 breast cancer cells specifically." (PMID 35645591, 2022). "Using a three-dimensional in vitro tumoral model we showed that the expression of lncMat2B, a lncRNA expressed in the hypoxic regions of multicellular tumor spheroids (MCTS), is increased in the CD44+/CD24- breast cancer cell subpopulation." (PMID 35626715, 2022). "OPN promotes tumor growth in breast cancer by activating the CD44/NF-kappa B pathway in cells with low integrin β3 levels." (PMID 36619897, 2022). "As recently shown, homophilic interactions of the CD44 protein in adjacent cancer cells are involved in the aggregation and metastasis of breast cancer cells." (PMID 35346305, 2022). "In highly invasive CD44 expressing breast carcinomas, tumor cells also express a hyaluronic acid binding protein that activates matrix metalloproteases (MMP) 2 and 9 on cell membranes." (PMID 36497364, 2022). "Our data also underscored the critical role of TRIM4 in breast cancer stem cells based on the observed proportions of CD44+/CD24− cells." (PMID 35843886, 2022). "It has been reported that CD44 expression correlates with tumor grade and tumor recurrence in breast cancer patients and also promotes metastasis." (PMID 36289750, 2022).
breast carcinoma (continued). "A wide number of breast cancer models currently support two distinct sub-populations of CSCs: a mesenchymal CSC population defined by CD44+/CD24− markers and an epithelial CSC population with ALDH+ markers." (PMID 35326728, 2022). "Inhibiting autophagy in triple-negative breast CSCs inhibited the STAT3/JAK2 pathway-mediated production of IL-6, a cytokine critical for CSC survival and required to produce the CD44+/CD24low phenotype in breast cancer cell lines." (PMID 35800881, 2022). "The CD44+/CD24− population was possessed as a specific surface marker for breast cancer stem cell identification, promoting cell proliferation and metastasis." (PMID 35631492, 2022). "As few as 100 CD24−/CD44+ BCSCs isolated from breast cancer tissues of patients were able to form tumors in immunocompromised mice." (PMID 36230903, 2022). "This represents the first time that the existence of breast cancer stem cells (BCSCs) was confirmed in breast cancer, with a phenotype of CD44+ CD24−/low." (PMID 36604141, 2022). "BMP-2 induces EMT and stemness of breast cancer cells through the Rb and CD44 signaling pathways, which act not only via Smad-dependent pathways but also via the PI3 kinase-Akt signaling pathway." (PMID 35693928, 2022). "We demonstrated that this population of breast cancer cells exhibit mesenchymal as well as cancer stem cell features, like high CD44 expression in vitro in spheroid model." (PMID 35879327, 2022). "Cosmc deficiency disrupts the CD44 O-glycosylation structure and subsequent inhibition of MAPK signaling leads to the inhibition of breast cancer cell growth in vivo." (PMID 35936713, 2022). "At the same time, phosphorylation and dephosphorylation play a crucial role in the regulation of the activities of CD44 and Stat3, and aberrant phosphorylation of CD44-Stat3 is linked with various tumor progressions, such as NPC, breast cancer and lung cancer." (PMID 36678534, 2022). "CD44 is a cancer stem-like cell marker, particularly breast cancer, and CD44 expression is related to metastatic disease and therapeutic resistance." (PMID 35626430, 2022). "BMP-2/5/6/7 are observed in breast cancers and are correlated with the expression of the stem cell marker CD44." (PMID 35693928, 2022). "In breast cancer, hyaluronan accumulation and CD44 overexpression correlate with higher incidence of metastases and poor patient outcomes." (PMID 36497283, 2022). "First, we sorted out the CD44+CD24− BCSC population from the clinical samples of breast cancer patients and detected the expression levels of stemness-related, chemoresistance-related, and self-renewal-related markers." (PMID 35301432, 2022). "The different isoforms of CD44, such as CD44s and CD44v6, have also been related to poor prognosis and metastasis in breast cancer." (PMID 35626430, 2022). "In another studies, etomoxir treatment reduced invasion rate of breast cancer cells and decreased sphere formation rate and the CD44 expression, a stemness marker, in lung adenocarcinoma sphere cells (H460)." (PMID 36221088, 2022). "For example, RHAMM couples with either CD44 in breast cancer cells or PDGFR in fibroblast cells to activate ERK1/2, in mediating cell migration." (PMID 36033439, 2022). "ROS is a key factor in maintaining the stemness of CD44+ breast cancer cells through upregulating the expression of CD44 and signal transducer and activator of transcription 3 (STAT3)." (PMID 36497050, 2022). "In breast cancer, the reduction of ESRP1 changes the variant expression of CD44v from CD44v to CD44, thus inhibiting its metastasis in the lung." (PMID 36052258, 2022). "An innovative electrochemical biosensor based on graphene quantum dots (GQDs) is developed for a simple, rapid, and highly sensitive primary diagnosis of the breast cancer biomarker cluster of differentiation-44 (CD44) antigen." (PMID 36354475, 2022). "According to the findings of this study, CD44-mediated cell fusion is critical in developing CSC in breast cancer cells." (PMID 36550571, 2022).
breast carcinoma (continued). "The Epi-Nio-HA group showed the most successful internalization into breast cancer cells, which was proved to be CD44-mediated." (PMID 35875198, 2022). "Upon injecting different populations into nonobese diabetic/severe combined immunodeficiency (NOD/SCID) mice only those cells of human breast cancer formed tumors that can express a CD44+ CD24low/−." (PMID 35800881, 2022). "To further support our data, we also characterized CD24−/CD44+ BCSCs from human luminal MCF-7 breast cancer cells." (PMID 35053617, 2022). "This study has added new information to the growing body of evidence that CD44 plays an important role in breast cancer metastasis and multidrug resistance." (PMID 36289750, 2022). "In our previous work, we developed a tetracycline-off regulated expression of CD44’s gene in the breast cancer (BC) cell line MCF-7 (B5 clone)." (PMID 35164076, 2022). "Tumor cells mainly bind to HA through the cluster of differentiation 44 (CD44), a widely expressed transmembrane protein that is a cell surface marker in breast carcinomas." (PMID 35198956, 2022). "Different studies have shown that the CD44 marker is more abundant in TNBC than other breast cancer subtypes." (PMID 35845934, 2022). "The results obtained from the electrochemical studies suggest a successful development of an efficient electrochemical biosensor for the selective, sensitive, and rapid detection of CD44 breast cancer biomarkers." (PMID 36354475, 2022). "On the other hand, the knockdown of CD44 suppressed the migration and invasion of breast cancer cells." (PMID 36289750, 2022). "We also provide evidence that the overexpression of CD44 in breast cancer markedly promoted cell migration and invasion abilities, while the opposite effects were observed upon CD44 knockdown." (PMID 36289750, 2022). "Recombinant BMP2 induces EMT and stemness of breast cancer cells via the Rb and CD44 signaling pathways, which leads to metastasis." (PMID 35846378, 2022). "In this study, KRT13 induced stem cell phenotypes in MCF7 breast cancer cells, and increased expression of stemness-related genes of CD44, c-Myc, ALDH1A1 and Nanog." (PMID 35078507, 2022). "Taken together, these results suggest that the C-terminal region of variant 3 is involved in TrkA binding and this is a general mechanism because it can be observed in breast cancer cells but also in cos7 in which the expression of TrkA and CD44 were induced." (PMID 35346305, 2022). "Increased expression of CD44 has been shown to enhance adhesion capacity of breast cancer cells through HGF signaling." (PMID 35565396, 2022). "We also evaluated the expression of ALDH1A3 and CD44, markers for breast cancer stem cells, in both control and RAB4A knockdown cells, and in the RAB4A knockdown cells that concurrently express either RAC1WT or RAC1CA." (PMID 36307864, 2022). "Adipose-derived stem cells fused with breast cancer cells showed the enrichment of CD44 + CD24-/low EpCAM+ CSC marker expression in the fusion cell population." (PMID 36550571, 2022). "To determine if CD81 regulates breast cancer metastasis like CD44, we assessed the clinical relevance of CD81 expression in human breast tumors and CTCs." (PMID 36193887, 2022). "CD44 constitutes a potential marker to enhance targeted therapy, indeed in breast cancer CD44-doxorubicin conjugated aptamers inhibited selective cell proliferation of CD44 expressing cells." (PMID 35211123, 2022). "CD44 overexpression in breast cancer cell lines significantly promoted cell migration and invasion abilities, whereas the opposite effects occurred upon the knockdown of CD44." (PMID 36289750, 2022). "The activation of this signaling pathway promotes the expression of the stem transcription factors SOX2 and NANOG, as well as CD44, which is one of the reported stem markers in breast cancer." (PMID 35954194, 2022).